ELOC (elongin C)
Description:
SIII, also known as elongin, is a general transcription elongation factor that increases the RNA polymerase II transcription elongation past template-encoded arresting sites. Subunit A is transcriptionally active and its transcription activity is strongly enhanced by binding to the dimeric complex of the SIII regulatory subunits B and C (elongin BC complex). In embryonic stem cells, the elongin BC complex is recruited by EPOP to Polycomb group (PcG) target genes in order generate genomic region that display both active and repressive chromatin properties, an important feature of pluripotent stem cells (By similarity). Core component of multiple cullin-RING-based ECS (ElonginB/C-CUL2/5-SOCS-box protein) E3 ubiquitin-protein ligase complexes, which mediate the ubiquitination of target proteins. By binding to BC-box motifs it seems to link target recruitment subunits, like VHL and members of the SOCS box family, to Cullin/RBX1 modules that activate E2 ubiquitination enzymes. Component the von Hippel-Lindau ubiquitination complex CBC(VHL). A number of ECS complexes (containing either KLHDC2, KLHDC3, KLHDC10, APPBP2, FEM1A, FEM1B or FEM1C as substrate-recognition component) are part of the DesCEND (destruction via C-end degrons) pathway, which recognizes a C-degron located at the extreme C terminus of target proteins, leading to their ubiquitination and degradation. The ECS(ASB9) complex mediates ubiquitination and degradation of CKB. As part of a multisubunit ubiquitin ligase complex, polyubiquitinates monoubiquitinated POLR2A. ECS(LRR1) ubiquitinates MCM7 and promotes CMG replisome disassembly by VCP and chromatin extraction during S-phase (By similarity). As part of the ECS(RAB40C) complex, mediates ANKRD28 ubiquitination and degradation, thereby inhibiting protein phosphatase 6 (PP6) complex activity and focal adhesion assembly during cell migration. The ECS(ASB7) complex acts a negative regulator of H3K9me3 histone mark by mediating ubiquitination and degradation of SUV39H1. As part of the ECS(LRRC58) complex, mediates CDO1 ubiquitination and degradation, regulating cysteine catabolism. (Microbial infection) Following infection by HIV-1 virus, component of a cullin-5-RING E3 ubiquitin-protein ligase complex (ECS complex) hijacked by the HIV-1 Vif protein, which catalyzes ubiquitination and degradation of APOBEC3F and APOBEC3G. The complex can also ubiquitinate APOBEC3H to some extent.
Synonyms: TCEB1; SIII
Tractability: Small molecule: a structure with a bound ligand is known; a high-quality ligand is known. PROTAC: UniProt records ubiquitination sites on it; ubiquitination databases record sites on it; a small molecule that binds it is known.
Gene: Protein-coding gene on chromosome 8 (73,939,169 to 73,972,307, reverse strand). Ensembl gene ENSG00000154582.
Subcellular location: Nucleus
Subcellular location (Human Protein Atlas): Vesicles; Cell Junctions; Nucleoli
Pathways (Reactome):
Disease: Evasion by RSV of host interferon responses; Formation of HIV elongation complex in the absence of HIV Tat; Formation of HIV-1 elongation complex containing HIV-1 Tat; HIV elongation arrest and recovery; Pausing and recovery of HIV elongation; Pausing and recovery of Tat-mediated HIV elongation; Tat-mediated HIV elongation arrest and recovery; Tat-mediated elongation of the HIV-1 transcript; Vif-mediated degradation of APOBEC3G
Gene expression (Transcription): Formation of RNA Pol II elongation complex; RNA Polymerase II Pre-transcription Events; RNA Polymerase II Transcription Elongation
Developmental Biology: M-decay: degradation of maternal mRNAs by maternally stored factors; Regulation of expression of SLITs and ROBOs
Immune System: Antigen processing: Ubiquitination & Proteasome degradation; Inactivation of CSF3 (G-CSF) signaling
Metabolism of proteins: Neddylation; Ribosome Quality Control (RQC) complex extracts and degrades nascent peptide
Cellular responses to stimuli: Oxygen-dependent proline hydroxylation of Hypoxia-inducible Factor Alpha
Gene Ontology:
Molecular function: protein binding; transcription corepressor binding; protein-macromolecule adaptor activity
Biological process: protein ubiquitination; target-directed miRNA degradation; transcription initiation at RNA polymerase II promoter; ubiquitin-dependent protein catabolic process via the C-end degron rule pathway; negative regulation of DNA-templated DNA replication; negative regulation of transcription by RNA polymerase II; proteasome-mediated ubiquitin-dependent protein catabolic process; regulation of transcription by RNA polymerase II; ribosome-associated ubiquitin-dependent protein catabolic process; ubiquitin-dependent protein catabolic process
Cellular component: Cul2-RING ubiquitin ligase complex; Cul5-RING ubiquitin ligase complex; elongin complex; cytosol; nucleoplasm; cytoplasm; nucleus; ubiquitin ligase complex
Genetic constraint (gnomAD): Loss-of-function variants: 0 observed, 9.84 expected, observed/expected ratio (o/e) 0, 90% interval 0 to 0.3. That is too few expected variants to judge how well the gene tolerates losing a copy. Missense variants: 37 observed, 140.96 expected, observed/expected ratio (o/e) 0.26, 90% interval 0.2 to 0.34. Synonymous variants: 40 observed, 49.76 expected, observed/expected ratio (o/e) 0.8, 90% interval 0.62 to 1.05.
Homologues: Orthologues: chimpanzee TCEB1 (100% identical), guinea pig ELOC (100% identical), macaque ELOC (100% identical), mouse Eloc (100% identical), rabbit ELOC (100% identical), tropical clawed frog eloc (100% identical), zebrafish elocb (99% identical), rat LOC134482331 (98% identical), Drosophila melanogaster EloC (92% identical), Caenorhabditis elegans elc-1 (75% identical), Caenorhabditis elegans elc-2 (48% identical), Caenorhabditis elegans F54F7.10 (39% identical).
Diseases named in the same sentence as ELOC in open-access papers:
ELOC is named in the same sentence as 41 diseases in open-access papers, as found by Europe PMC text mining. Sharing a sentence is not in itself a finding about the gene and the disease. The quoted sentences say what the papers report.
renal cell carcinoma (12 papers, 2014 to 2025). "ELOC (also referred to as TCEB1)-mutated renal cell carcinoma (ELOC-mutated RCC) is a rare, molecularly defined RCC newly incorporated into the 2022 5th Edition WHO Classification of Tumours of the Urinary and Male Genital Organs." (PMID 41357565, 2025). "A significant update in this edition is the inclusion of a new category for molecularly defined renal neoplasms, such as TFE3-rearranged renal cell carcinoma and ELOC-mutated RCC." (PMID 41463280, 2025). "The characteristics of ELOC-mutated RCC, clear cell papillary renal cell tumor, and renal cell carcinoma with fibromyomatous stroma." (PMID 41357565, 2025). "We summarize the characteristics of ELOC-mutated RCC, clear cell papillary renal cell tumor, and renal cell carcinoma with fibromyomatous stroma." (PMID 41357565, 2025). "ELOC(TCEB1)-mutant renal cell carcinoma [ELOC(TCEB1)-RCC] is a newly recognized type of RCC characterized by clear cell morphology and ELOC(TCEB1) gene mutation." (PMID 41306531, 2025). "Accurate diagnosis is crucial, as RCC-FMS must be distinguished from other renal cell carcinomas (e.g., clear cell RCC, clear cell papillary RCC, ELOC-mutated RCC) with different management strategies and prognoses." (PMID 41367859, 2025).
renal carcinoma (4 papers, 2024 to 2025). A carcinoma arising from the epithelium of the renal parenchyma or the renal pelvis. "The molecularly defined renal carcinomas include TFE3-rearranged RCC, TFEB-altered RCC, ELOC-mutated RCC, FH-deficient and SDH-deficient RCC, ALK-rearranged RCC, and SMARCB1-deficient renal medullary carcinomas." (PMID 38235567, 2024). "Indeed recent advances have identified new entities in renal carcinoma with clear cell morphology and VHL wild type phenotype such as TFE3-rearranged RCC, ELOC (formely TCEB1)-mutated RCC or clear cell renal papillary tumor." (PMID 40771659, 2025).
von Hippel-Lindau syndrome (3 papers, 2016 to 2022). "Of the well-known adaptors of E3 ligase, we selected von Hippel-Lindau syndrome (VHL) and HIV-1 virion infectivity factor (VIF), which are adaptors for the complex including elongin B, elongin C, and cullin-2/5 that possesses E3 ubiquitin ligase activity." (PMID 27322423, 2016).
breast carcinoma (2 papers, 2018 to 2021). "We show that in breast cancer cells Rab40b does bind to the CRL5 E3 ligase complex containing Cullin5, Elongin B, Elongin C, and Rbx2 and that mutations to the Rab40b–SOCS box are sufficient to disrupt this interaction." (PMID 33999101, 2021).
clear cell renal carcinoma (2 papers, 2014 to 2021). A malignant epithelial neoplasm of the kidney characterized by the presence of lipid-containing clear cells within a vascular network. "A candidate gene for such an alteration is TCEB1, which encodes the required VHL binding partner elongin C and, in the recent genomic sequencing of clear cell renal carcinoma was found to be somatically mutated in the minority of cases that do not harbor VHL mutations." (PMID 25589003, 2014).
colorectal cancer (2 papers, 2024). A primary or metastatic malignant neoplasm that affects the colon or rectum. "The deSUMOylation of ELOC induced by SENP1 promoted USP51 bind to ELOC and facilitated the deubiquitylation and stabilization of HIF-1α, consequently enhancing colorectal cancer cells stemness." (PMID 38389923, 2024).
virus infection (2 papers, 2011 to 2014). "The initial purpose of engineering mutations within the elongin C biding domain of NS1 was to investigate if NS1 did form an E3 ligase complex to degrade STAT2 in a live virus infection, and to alter this function, such that STAT2 degradation was reduced during RSV infection." (PMID 21600055, 2011). "It will be meaningful to carry out additional investigations to determine the role of Elongin C during the life cycles of different virus species, which, in turn, may further define the function of plant Elongin C in the absence of virus infection." (PMID 24954157, 2014).
glioma (1 paper, 2020). A benign or malignant brain and spinal cord tumor that arises from glial cells (astrocytes, oligodendrocytes, ependymal cells). "In this study, we demonstrated that overexpression of the CRL5 components Elongin B, Elongin C, SOCS3 and Rbx2 predicts poor prognosis of glioma and all GBM subclasses." (PMID 32931454, 2020).
head and neck squamous cell carcinoma (1 paper, 2022). A squamous cell carcinoma that arises from any of the following anatomic sites: lip and oral cavity, nasal cavity, paranasal sinuses, pharynx, larynx, and salivary glands. "Notably, gains and amplifications in ELOC were prevalent in head and neck squamous cell carcinoma (63.8%) and HCC (55.7%)." (PMID 35664333, 2022).
Huntington disease (1 paper, 2015). Huntington disease (HD) is a rare neurodegenerative disorder of the central nervous system characterized by unwanted choreatic movements, behavioral and psychiatric disturbances and dementia. "Inhibition of elongin C also delayed paralysis in a C. elegans model of Huntington's disease that expresses a polyglutamine protein, in a HIF‐1‐dependent manner." (PMID 26361075, 2015).
Insulin resistance (1 paper, 2021). Increased resistance towards insulin, that is, diminished effectiveness of insulin in reducing blood glucose levels. "Additionally, mindbomb E3 ubiquitin protein ligase 2 (MIB2), anaphase promoting complex subunit 1 (ANAPC1), and ELOC, Elongin C (TCEB1), are also involved in ubiquitination, which can affect the development of insulin resistance and MetS." (PMID 34516309, 2021).
Renal Angiomyoadenomatous Tumor (1 paper, 2025). A very rare, benign, encapsulated tumor that arises from the kidney. "Unlike CCPRCT or related renal angiomyoadenomatous tumors, ELOC-mutated RCC lacks prominent subnuclear vacuoles, and CCPRCT typically shows a “cup-shaped” CA9 staining pattern." (PMID 41357565, 2025).
retinal hemangioblastoma (1 paper, 2019). A hemangioblastoma that arises from the retina.
tumor (19 papers, 2011 to 2025). "Next-generation sequencing (NGS) revealed a ELOC p.Y79C gene mutation in tumor cells, leading to the definitive diagnosis of ELOC-mutated RCC." (PMID 41357565, 2025). "The utilization of molecular testing is necessary to identify the presence of a mutation in the ELOC gene (TCEB1) and classify the tumour as an ELOC-mutated RCC." (PMID 38765391, 2024). "Recently, one tumor with confirmed monosomy 8 and ELOC deletion as well as a TSC1 mutation was documented." (PMID 34885018, 2021). "Considering a half of the tumor‐driven pVHL mutations harbor in α domain of pVHL, which interferes with its ability to bind elongin C and leads to the loss of pVHL protein stability, we propose that OTUD6B overexpression resists HIF‐1α accumulation in tumor cells with pVHL α domain mutations." (PMID 32328410, 2020). "Our data showing the reduced expression of the SOCS2 L163P and C167F SOCS-box and the R73E SH2-domain mutants, which are defective in Elongin C interaction lend support to these hypotheses and is in line with previous data from studies with VHL tumour suppressor SOCS-box point mutations." (PMID 21980433, 2011). "The tumor cells showed expression of PAX8, CA9, AMACR/P504S, Vimentin, CK7, CD10, FH, INI1(SMARCB1) and ELOC(TCEB1), and ELOC was mainly located in the nucleus." (PMID 41306531, 2025). "Immunologically, tumor cells are positive for CA9 and CK7, and ELOC shows nuclear positivity." (PMID 41306531, 2025). "Among them, tumor cells showed moderate positivity for CK7; CA9 showed diffuse strong positive membrane staining, completely outlining the cell membrane; ELOC was moderate positive, mainly localized in the nucleus, with varying degrees in staining intensity and range." (PMID 41306531, 2025). "In fact, it is not clear whether TSC/MTOR and ELOC mutated RCC with fibromyomatous stroma are two different tumor types, or just part of the molecular genetic variability within one tumor entity." (PMID 34885018, 2021).
cancer (11 papers, 2017 to 2025). A tumor composed of atypical neoplastic, often pleomorphic cells that invade other tissues. "ELOC was the most commonly altered component across all cancer types, and was frequently gained (35.4%)." (PMID 35664333, 2022). "EPOP, Elongin B, and Elongin C are often upregulated in cancer and systematic CRISPR screening experiments demonstrated that they are “common essential” in human cancer cell lines, meaning that they are required for efficient proliferation in most human cancer cells." (PMID 35193659, 2022). "For instance, CUL2, RBX1, ELOB, and ELOC are known to interact with PRAME, a substrate-recognition subunit that is overexpressed in a variety of cancers, including HCC." (PMID 35664333, 2022). "To gain a pan-cancer perspective on alterations to these genes, we evaluated the DNA CN status of VHL, CUL2, RBX1, ELOC, and ELOB across 33 cancer types processed by TCGA." (PMID 35664333, 2022).
infection (1 paper, 2020). The state of being infected such as from the introduction of a foreign agent such as serum, vaccine, antigenic substance or organism. "Since on the other hand protein levels of all Elongins remained unchanged under infection, the diminished Elongin C signal in wt LACV-infected cells apparently derived from a relocalization and dilution throughout the cell." (PMID 31941775, 2020). "Thus, infection with the NSs-expressing wt LACV converted the nuclear Elongin C speckles in a manner that was unique and clearly distinct from α-amanitin." (PMID 31941775, 2020). "Using LMB, we could indeed trap Elongin C in the nucleoli of HuH-7 cells infected with wt LACV at an MOI of 1 (although the signal was somewhat weaker than in mock infection)." (PMID 31941775, 2020). "From the different phenotypes of infection and α-amanitin we conclude that the redistribution of Elongin C is specific for LACV NSs and not simply a consequence of its ability to block RNAP II." (PMID 31941775, 2020).
ELOC also shares sentences with these, for which no sentence is quoted: kidney neoplasm (4 papers); prostate carcinoma (4); renal medullary carcinoma (3); Renal neoplasm (3); kidney cancer (2); oncocytic tumour (2); papillary renal cell carcinoma (2); asthma (1); cervical cancer (1); collecting duct carcinoma (1); follicular carcinoma (1); head and neck cancer (1); hemangioblastoma (1); hereditary leiomyomatosis (1); malaria (1); Medullary carcinoma (1); microphthalmia (1); neuroblastoma (1); ovarian carcinoma (1); ovary cancer (1); papillary adenoma (1); pheochromocytoma (1); polycythemia (1); spindle cell carcinoma (1); Tumours of the Urinary System (1).